NR4A3 (nuclear receptor subfamily 4 group A member 3)
Diseases named in the same sentence as NR4A3 in open-access papers (continued):
Sharing a sentence is not in itself a finding about the gene and the disease.
lymphoma (12 papers, 2019 to 2025). A malignant (clonal) proliferation of B- lymphocytes or T- lymphocytes which involves the lymph nodes, bone marrow and/or extranodal sites. "Nr4a1 and Nr4a3 also regulate several different types of lymphoma, including non-Hodgkin’s and B-cell." (PMID 31683815, 2019). "Moreover, overexpression of NR4A1 or NR4A3 in lymphoma cells induced apoptosis, supporting a tumor-suppressive function in lymphomas." (PMID 36831639, 2023). "In aggressive lymphoma, NR4A3 has powerful tumor suppressor function similar to NR4A1." (PMID 33407456, 2021). "The reactivation of NR4A3 by lncNR4A3 could have similar tumor suppressor effect in the context of lymphoma and other malignancies." (PMID 33330042, 2020). "This shows that Nr4a1 and Nr4a3 controls induction of apoptosis in different lymphoma cells." (PMID 31683815, 2019). "An induction of pro-apoptotic genes and enhancement of apoptosis was also seen when treating leukemia and most lymphoma cells in vitro with drugs that induce the expression of NR4A1 and NR4A3." (PMID 36831639, 2023). "While in solid tumor-derived cell lines, NR4A1 and NR4A2 expression are high, and both receptors exhibit pro-oncogenic activities, in blood-derived tumors (leukemias and lymphomas), NR4A expression, particularly of NR4A1 and NR4A3, is low." (PMID 36831639, 2023). "It was indicated that in the case of lymphomas, pharmacotherapy aimed at increasing the expression of NR4A1 and NR4A3 is justified." (PMID 35625926, 2022). "However, in a study, no hypermethylation was reported in the NR4A1 and NR4A3 genes in aggressive lymphomas." (PMID 40028473, 2025).
extraskeletal myxoid chondrosarcoma (11 papers, 2011 to 2025). A rare malignant soft tissue neoplasm of uncertain differentiation, characterized by the presence of chondroblast-like cells in a myxoid stroma and a multinodular growth pattern. "NR4A3 encodes an orphan nuclear receptor for which the function is only partially known but NR4A3 fusion genes are associated with tumour development such as extraskeletal myxoid chondrosarcoma." (PMID 38571883, 2024). "NR4A3 expression has also been linked to oncogenesis in extraskeletal myxoid chondrosarcoma and its overexpression in pancreatic β-cell proliferation and liver regeneration." (PMID 32867110, 2020). "Extraskeletal myxoid chondrosarcoma (EMC) is an ultra-rare, soft tissue sarcoma driven by chromosomal translocations involving the gene NR4A3." (PMID 41321774, 2025). "SIX3 regulates the transcriptional activity of the orphan nuclear receptor NOR-1 (NR4A3), which regulates the survival of cells, and acts as a part of the EWS/NOR-1 fusion protein, implicating the oncogenesis of human extraskeletal myxoid chondrosarcoma (EMC)." (PMID 21962230, 2011).
atherosclerosis (10 papers, 2017 to 2025). A disease characterized by the build-up of fatty material and calcium deposition in the arterial wall resulting in partial or complete occlusion of the arterial lumen. "Our previous study showed that glycated ApoA-IV induces NR4A3 expression and that NR4A3 deficiency attenuates atherosclerosis progression." (PMID 41438090, 2025). "This is consistent with the contribution of NR4A3 deficiency in hematopoietic stem cells to myelopoiesis, monocyte differentiation, and atherosclerosis development in vivo." (PMID 34248958, 2021). "NR4A3 deficiency reduces vascular injury and atherosclerosis in mice." (PMID 41438090, 2025). "While Nr4a3 promotes T cell proliferation through dendritic cells, mice with bone marrow transplanted from Nr4a3 deficient mice have more granulocyte-macrophage precursors and macrophage and dendritic cell progenitors, which is linked to increased plaque formation in atherosclerosis." (PMID 31683815, 2019). "Nuclear receptor subfamily 4 group A member 3 (NR4A3) is emerging as a critical regulator not only in the progression of atherosclerosis but also in the pathogenesis of arterial calcification." (PMID 41440006, 2025). "Previous researches have suggested that NR4A3 acts as a pro‐proliferation factor involved in atherosclerosis by enhancing cell viability and mediating cell cycle (inducing cyclin D1 and D2 expression)." (PMID 33942991, 2021). "Nr4a3 deletion in hematopoietic stem cells (HSCs) accelerated atherosclerosis formation." (PMID 36293311, 2022). "Indeed, several studies reported that NR4A3 serves as a significant player involved in vascular‐related disorders for it has been demonstrated that exert promote proliferation and migration in vascular smooth muscle cells, for instance, Atherosclerosis, Coronary artery disease." (PMID 33942991, 2021). "Intriguingly, both NR4A3 and MIP-3α have been shown to play crucial roles in the pathogenesis of atherosclerosis, and here, we show an enhancement and correlation in gene expression of both in carotid plaques from symptomatic patients." (PMID 28167941, 2017).
lung carcinoma (9 papers, 2019 to 2025). "A study in 2019 found that the upregulation of KLF11 and NR4A3 is associated with the induction of apoptosis and ROS generation and is critical for slowing the progression of lung cancer." (PMID 37107299, 2023). "A549 lung cancer cells exhibited increased levels of NR4A3 and KLF11 after combination therapy, which also induced apoptosis and inhibited cell proliferation by elevating intracellular ROS levels." (PMID 37107299, 2023). "As part of this study, patient survival analysis, using a publicly available clinical data repository, was conducted, establishing that high levels of NR4A3 expression positively correlate with increased survival rates for patients with breast and lung cancers." (PMID 33634114, 2021). "Similarly, expression of SPRY1 and NR4A3 has been observed in CD103+ TRM in lung cancer." (PMID 32471032, 2020).
leukemia (8 papers, 2016 to 2025). A malignant (clonal) hematologic disorder, involving hematopoietic stem cells and characterized by the presence of primitive or atypical myeloid or lymphoid cells in the bone marrow and the blood. "Remarkably, in all three patients, NR4A3 expression levels were relatively higher after the ATRA leukemia cell differentiation treatments, whereas the expression levels of NR4A1 were not consistently or overtly altered." (PMID 36040481, 2022). "In contrast, based on the results of NRA41 and NR4A3 knockout studies on mice, it was shown that the dual knockdown of both NR4A1 and NR4A3 in mice resulted in the development of leukemia, and NR4A1 and NR4A3 exhibited tumor suppressor-like activities in most blood-derived tumors." (PMID 37175855, 2023). "To evaluate the durability of PRDM1/NR4A3 double KO CAR T-cell therapeutic efficacy, we conducted a study in which CAR T-cell-treated NSG mice were rechallenged with NALM-6 cells 40 days after the initial leukemia cell transfer." (PMID 36350986, 2022).
melanoma (8 papers, 2019 to 2025). A malignant, usually aggressive tumor composed of atypical, neoplastic melanocytes. "The Grey mutation is associated with upregulated expression of both Syntaxin 17 and the neighbouring NR4A3 gene in Grey horse melanomas." (PMID 38571883, 2024). "Both STX17 and the neighbouring NR4A3 (nuclear receptor subfamily 4, group A, member 3) gene are overexpressed in melanomas from grey horses." (PMID 32652526, 2020). "The transcription of Nr4a2 and Nr4a3 was upregulated in CD8+ TILs in an autochthonous melanoma mouse model." (PMID 33597928, 2020). "However, the exact mechanism leading to melanomagenesis is still poorly understood but both STX17 and NR4A3 have possible links to tumour development including relevance for melanomas." (PMID 38571883, 2024). "Similarly, the analysis of human melanoma TILs scRNA-Seq data highlighted a correlation of Nr4a1, Nr4a2, and Nr4a3 transcription with inhibitory receptor expression (Pdcd1 and Havcr2)." (PMID 33597928, 2020). "Expression analysis of Grey horse melanoma tissue first demonstrated that both STX17 and NR4A3 show upregulated expression from the Grey chromosome in heterozygotes." (PMID 38571883, 2024). "Expression analysis using grey horse melanomas showed that both STX17 and the neighbouring gene NR4A3 show upregulated expression from the Grey allele in heterozygous horses." (PMID 38571883, 2024). "Interestingly, TNF-α signalling via the NF-κB pathway was significantly downregulated with a reduction ranging from 7- to 40-fold in expression of some of its prooncogenic target genes (e.g., JUNB, FOS, DUSP1) and melanoma-related genes (e.g., EGR3, NR4A3, CCN1)." (PMID 34497073, 2021).
acinic cell carcinoma (7 papers, 2019 to 2025). "Moreover, NR4A3 has been identified as one of the diagnostic biomarkers for acinar cell carcinoma due to its high sensitivity and specificity." (PMID 39474111, 2024). "Acinic cell carcinoma (AcCC) is a morphologically distinctive salivary gland malignancy often associated with chromosome rearrangements leading to overexpression of the NR4A3 transcription factor." (PMID 32867110, 2020). "NR4A3 negativity is useful in differential diagnosis with acinic cell carcinoma, and GATA3 positivity differentiates it from salivary duct carcinoma." (PMID 41440486, 2025). "Although data indicate that NR4A3 acts as an oncogene in AciCC (acinic cell carcinoma) and some other tumors, its tumor suppressor role is more evident in many malignancies." (PMID 39664575, 2024). "The latest molecular genetic findings demonstrate that NR4A3 rearrangements, which are a hallmark of acinic cell carcinoma (AciCC) of the salivary gland, are consistently absent in acinic cell carcinoma of the breast." (PMID 41301002, 2025). "For acinic cell carcinoma, approximately 60–100 cases have been reported with molecular studies definitively distinguishing breast primaries from salivary gland counterparts through absence of NR4A3 rearrangements." (PMID 41301002, 2025). "We report that most, if not all salivary gland acinic cell carcinomas (AcCC) harbor translocations that result in activation of the NR4A3 or NR4A2 genes." (PMID 32867110, 2020).
Insulin resistance (7 papers, 2009 to 2025). Increased resistance towards insulin, that is, diminished effectiveness of insulin in reducing blood glucose levels. "Loss or downregulation of Nr4a3 (Log2FC = −5.87), Scd1 (Log2FC = −2.24), Chrna4 (Log2FC = −4.23), and Fabp5 (Log2FC = −3.82) increase glucose intolerance, insulin resistance, diet-induced fatty liver disease, and cholinergic anti-inflammatory pathways." (PMID 35004828, 2021). "Furthermore, as IRLnc could directly regulate the expression of NR4A3 which associated with insulin resistance, we inferred that IRLnc may be a potential therapeutic target for insulin resistance and type 2 diabetes." (PMID 33522899, 2021). "Previous studies have shown that NR4A3 gene expression is reduced in skeletal muscles and adipose tissues from multiple rodent models of insulin resistance." (PMID 33522899, 2021). "Nr4a3 expression is reduced in skeletal muscle and adipose tissue in multiple rodent models of insulin resistance, while increased expression of Nr4a3 increases insulin responsiveness and GLUT4 translocation." (PMID 23349861, 2013). "In this study, we assessed whether common genetic variation within the NR4A3 locus, encoding Nor-1, contributes to the development of prediabetic phenotypes, such as glucose intolerance, insulin resistance, or β-cell dysfunction." (PMID 19682370, 2009). "However, we did not detect any convincing associations between the selected NR4A3 tagging SNPs and glucose intolerance/insulin resistance in the two investigated study cohorts." (PMID 19682370, 2009). "Further regulatory network analysis revealed that insulin resistance and sensitivity pathways were modulated through key genes, including IRS2, CPE, ADRB2, NR4A3, and FGF19." (PMID 40969325, 2025). "NR4A3 (NOR1) regulates skeletal muscle adaptation, mitochondrial biogenesis, and metabolic homeostasis, with implications for enhancing endurance performance and addressing metabolic conditions such as insulin resistance, heart disease, and hypertension." (PMID 40926269, 2025).
diabetes (6 papers, 2009 to 2025). "As recent GWA studies mainly detected genes involved in insulin secretion as diabetes risk genes, one may assume that NR4A3 genetic variants have an impact on diabetes prevalence." (PMID 19682370, 2009). "Thus, NR4A3 represents a novel candidate gene for β-cell function which was not covered by the SNP arrays of recent genome-wide association studies for type 2 diabetes mellitus." (PMID 19682370, 2009). "Since the METSIM Study design also allows the analysis of NR4A3 genetic variants for the endpoint diabetes in a population-based cohort, we tested whether rs1526267, rs12686676 or rs10819699 associated with the prevalence of diabetes." (PMID 19682370, 2009). "In addition, upregulation of NR3C4 can be used as potential biomarker for type 2 diabetes whereas downregulation of two NRs including NR3C3 and NR4A3 can only be used as biomarkers for diabetes with rheumatoid arthritis as a complication." (PMID 29065888, 2017). "A total of 882 METSIM participants (59 ± 6 years) genotyped for NR4A3 were diagnosed with diabetes." (PMID 19682370, 2009). "We are confident that the described association between NR4A3 genetic variants and insulin secretion is not a by-chance finding, and that further research on the role of orphan nuclear receptors in beta cell function and diabetes pathogenesis is warranted." (PMID 19682370, 2009). "Interestingly, most diabetes genes detected by the GWA studies are also involved in insulin secretory function, as it is the case for NR4A3." (PMID 19682370, 2009).
type 2 diabetes (6 papers, 2009 to 2023). "Based on the gene array, we found that skin γδ T cells differentially express NR4A1 and NR4A3, two orphan nuclear receptors which have been shown to sensitize muscle to insulin and have been reported to be underexpressed in obesity and type 2 diabetes." (PMID 20625397, 2010).
myocardial infarction (5 papers, 2021 to 2025). Gross necrosis of the myocardium, as a result of interruption of the blood supply to the area, as in coronary thrombosis. "NR4A3 is associated with a reduction in macrophages in animal models and humans with myocardial infarction and cardiac hypertrophy." (PMID 40725010, 2025). "After a myocardial infarction, Nr4a3 reduces the size of the infarct, enhances left ventricular function, and lessens the inflammatory response that was triggered." (PMID 39408930, 2024). "NR4A3 over-expression inhibited the NF-κB signaling in a mouse model of myocardial infarction, by decreasing IκBα phosphorylation and inhibiting p65 nuclear translocation." (PMID 35115943, 2021). "Another study revealed that Nr4a3 may reduce myocardial inflammatory responses through JAK2-STAT3/NF-kB signaling and make it a potential therapeutic target for heart remodeling following myocardial infarction." (PMID 39408930, 2024). "It is reported that NR4A3 overexpression could increase the activity of JAK2/STAT3 signaling in the heart of mice after myocardial infarction and alleviate the inflammatory response after myocardial infarction." (PMID 35747513, 2022).
bladder cancer (4 papers, 2021 to 2025). "In summary, this study demonstrated that low expression of NR4A3 is associated with bladder cancer progression and poor prognosis." (PMID 40762284, 2025). "In bladder cancer, miR-20a-5p promoted growth and metastasis by inhibiting the expression of the tumor suppressor gene NR4A3." (PMID 37829050, 2023). "MiR-20a-5p promoted the growth and metastasis of the bladder cancer cells by inhibiting the expression of the tumor suppressor gene NR4A3 and played a carcinogenic role in BCa." (PMID 34925506, 2021). "To verify the relationship between NR4A3 and miR-20a-5p, we simultaneously transfected NR4A3 plasmids and miR-20a-5p mimics into the bladder cancer cells." (PMID 34925506, 2021). "In this study, we aimed to investigate the role of miR-20a-5p and NR4A3 in bladder cancer and the regulatory relationship between them." (PMID 34925506, 2021). "The cell proliferation detection results showed that NR4A3 overexpression inhibited the proliferation of the bladder cancer cells." (PMID 34925506, 2021). "The results of NR4A3 expression in the bladder cancer showed that NR4A3 was highly expressed in the tissues of patients with bladder cancer compared with the paracancer control group." (PMID 34925506, 2021). "In a bladder cancer model, it was found that silencing NR4A3 in bladder cancer T24 and 5637 cells could enhance cell proliferation and migration, whereas overexpression of NR4A3 could inhibit the malignant phenotype of bladder cancer." (PMID 37587470, 2023). "Importantly, we further demonstrate that miR-20a promotes EMT, migration, invasion, and metastasis of the bladder cancer cells by targeting NR4A3." (PMID 34925506, 2021). "The results also showed that NR4A3 was significantly downregulated in bladder cancer." (PMID 34925506, 2021). "The miR-20a-5p mimics promoted the proliferation of the bladder cancer cells, whereas NR4A3 could reverse the proliferation of miR-20a-5p." (PMID 34925506, 2021). "Here, it was found that NR4A3 was significantly lower expressed in patients with bladder cancer, whereas JorA could increase NR4A3 expression in bladder cancer T24 cells, suggesting that JorA may exert its tumor suppressor effect through the regulation of NR4A3." (PMID 37587470, 2023). "In addition, the reduction of NR4A3 could promote the proliferation, invasion, and clonal formation of the bladder cancer cells 5637 and T24." (PMID 34925506, 2021). "Transwell test results showed that NR4A3 overexpression inhibited the invasion ability of the bladder cancer cells, and the miR-20a-5p mimics promoted the invasion ability of the bladder cancer cells, whereas NR4A3 could reverse the invasion ability of miR-20a-5p." (PMID 34925506, 2021). "NR4A3 and MYCT1 genes, whose expression was increased by JorA, were found to be lowly expressed in bladder cancer samples in clinical cases." (PMID 37587470, 2023). "However, whether miR-20a-5p targets NR4A3 in bladder cancer progression is unknown." (PMID 34925506, 2021). "Therefore, in bladder cancer, miR-20a may activate the MEK signaling pathway by inhibiting NR4A3, thereby promoting EMT and promoting the proliferation and metastasis of bladder cancer." (PMID 34925506, 2021).
chondrosarcoma (4 papers, 2009 to 2024). A malignant cartilaginous matrix-producing mesenchymal neoplasm arising from the bone and soft tissue. "TCF3 is translocated to a number of fusion partners in pre- and pro-B-ALL, while TCF12 is fused to NR4A3 in extraskeletal mixoid chondrosarcoma." (PMID 19461887, 2009). "The same holds true for rearrangements involving NR4A3 in extraskeletal myxoid chondrosarcomas: while the AMP-FPS assay covers the most NR4A3 common partners (EWSR1, TAF15, TCF12, TFG) it lacks probes for both NR4A3 and uncommon partners, thus scoring negative in the presence of alternative fusions." (PMID 32351889, 2020).
Ewing sarcoma (4 papers, 2022 to 2025). A small round cell tumor that lacks morphologic, immunohistochemical, and electron microscopic evidence of neuroectodermal differentiation. "The EWRS1 fusion corresponded to Ewing sarcoma (FL1 gene) and EMCS (NR4A3 gene), and the SS18-SSX fusion corresponded to synovial sarcoma, as would be expected." (PMID 36430703, 2022).